TNF (tumor necrosis factor)
Diseases named in the same sentence as TNF in open-access papers (continued):
Sharing a sentence is not in itself a finding about the gene and the disease.
Arthritis (continued). "The importance of the proinflammatory cytokines TNF-α and lymphotoxin (LT)-α in an experimental model of S. aureus sepsis and arthritis was examined by Hultgren and colleagues." (PMID 17129374, 2006). "Paw sections from human tumor necrosis factor transgenic mice, which develop an erosive arthritis, were analyzed at three different skeletal sites: subchondral bone erosions, adjacent cortical bone channels, and endosteal regions distant from bone erosions." (PMID 16507121, 2006). "Our data revealed the involvement of interferon-γ, TNF-α, and transforming growth factor-β signaling pathways during arthritis development in the CIA model, which is consistent with previous studies." (PMID 16507131, 2006). "The majority of studies of the regulation of cytokines and destructive enzymes in arthritis have relied on the stimulation of outgrown synovial fibroblasts with various catalytic molecules, among them TNF-α and IL-1β." (PMID 17177994, 2006). "Activity of arthritis was determined by routine parameters for systemic inflammation, by histological scoring of synovitis and by semiquantitative RT-PCR of IL-1β, TNF-α, stromelysin and collagenase I in synovial tissue." (PMID 16542506, 2006). "The fact that the IL-32-related cytokines, TNFα and IL-18, show a close correlation with arthritis implies that IL-32 has a pathologic role in inflammatory diseases." (PMID 17078892, 2006). "TNF blockage was effective in the early period, and following anti-IL-1 treatment was effective on the blockage of arthritis and joint destruction, he said." (PMID 23674954, 2005). "In this study, changes in chondrocyte phenotype and function were determined following treatment with TNF-α and EGF, mediators that contribute to sustaining the inflammatory processes associated with arthritis." (PMID 15642133, 2005). "TNF-α is one of the best-known inflammatory cytokines and is involved in a number of inflammatory diseases including arthritis." (PMID 15833111, 2005). "To study the role in vivo of JNK1 activation in TNF-mediated arthritis, we intercrossed hTNFtg with JNK1-/- mice." (PMID 15642137, 2005). "This is exemplified in transgenic mice overexpressing the human TNF-α gene; these mice exhibit an erosive arthritis, which is improved by administration of OPG, of neutralizing anti-TNF-α antibodies, or of the bisphosphonate pamidronate." (PMID 15642143, 2005). "There was a study showed that TNF-α blocker is valid in the early arthritis, but the treatment of the anti- IL-1 can prevent the arthritis from developing continuously and the cartilage destruction." (PMID 23674954, 2005). "Of interest, arthritis in hTNFtg mice is directly induced by overexpression of TNF, a potent trigger of the JNK pathway." (PMID 15642137, 2005). "Among numerous cytokines, people have confirmed that the IL-1, TNF-α played a key role in arthritis progression." (PMID 23674954, 2005). "This is at odds with more systemic models of arthritis, such as collagen-induced and adjuvant arthritis, in which there is highly significant TNF-α elevation in LN and/or spleen." (PMID 15899031, 2005). "Although MSC possess immunosuppressive capacities, we have previously shown that they are unable to display a benefit in the collagen-induced arthritis model because they lose this property in the presence of TNF-α." (PMID 16277684, 2005). "We have previously shown that TNF autovaccination successfully generates high anti-TNF antibody titres, blocks TNF and ameliorates collagen-induced arthritis in DBA/1 mice." (PMID 15026813, 2004). "We thank Ferring Pharmaceutical for the funding of this research, Pharmexa for providing valuable advice with regard to the TNF autovaccination, and thank Cancer Research (UK) and the Arthritis and Rheumatology Campaign." (PMID 15026813, 2004).
Arthritis (continued). "When we previously used TNF autovaccination in a murine collagen-induced arthritis model, we found that this resulted in the generation of high titres of anti-TNF antibodies that ameliorated the disease and decreased the severity of arthritis." (PMID 15026813, 2004). "In vivo, GHTFs treatment reduced clinical arthritis scores by over 40%, alleviated synovial hyperplasia, preserved collagen volume fraction, and lowered serum levels of TNF-α and IL-1β, demonstrating superior overall efficacy compared to AF and methotrexate (P >0.05)." (PMID 41869362, 2026). "Previous research has demonstrated that Guanjietong Pian in conjunction with arthroscopic cleaning for arthritis patients can decrease the amount of interleukin-6 and tumor necrosis factor-α in patients with osteoarthritis of the knee and postpone the need for an artificial joint replacement." (PMID 40295239, 2025). "Walnut leaf ethanolic extract ameliorated acute inflammation and arthritis in rats by increasing the levels of blood IL‐4, besides attenuating TNF‐α, NF‐κB, IL‐6, IL‐16, COX‐2, and prostaglandin E2 (PGE2) amounts in blood, which resulted in reduced paw edema and arthritic development." (PMID 41179368, 2025). "Decreased arthritis aggravation and TNF and IL-17 production in KO mice with periodontitis." (PMID 40248692, 2025). "TNF inhibitors are effective for steroid-refractory arthritis, while IL-6 inhibitors may be preferred in cases with systemic inflammatory features." (PMID 41239350, 2025). "Furthermore, the EGF levels were increased in patients with arthritis and positively correlated with TNF-α expression." (PMID 41012652, 2025). "Also, in the induction phase of arthritis, T cell‐derived TNF is protective against arthritis development through the control of autoreactive T cell responses." (PMID 40977146, 2025). "Non-tumor necrosis factor biologics, particularly rituximab and tocilizumab, may represent promising options for refractory arthritis." (PMID 40725689, 2025). "Notably, the secreted level of TNF‐α, which is highly relevant to arthritis, was significantly decreased after Wj1113 treatment, and Wj1113's inhibitory effect surpassed that of the positive drug." (PMID 40626319, 2025). "While the ankle joint and TMJ displayed significant changes in gene expression under arthritic conditions compared to controls, the gene expression in the alveolar bone remained unaffected by chronic TNF-mediated arthritis, as revealed by principal component analysis." (PMID 40755771, 2025). "A cohort study involving patients with ICI-induced arthritis and matched controls revealed significantly elevated serum levels of vascular endothelial growth factor-A (VEGF-A) and TNF-α in the ICI-induced arthritis group, along with increased levels of IFN-γ and IL-6." (PMID 41239350, 2025). "At the age of 17 years, the patient developed frank arthritis, which required anti-TNF therapy." (PMID 40725177, 2025). "Pro-inflammatory cytokines (tumor necrosis factor-alpha [TNF-α], interleukin [IL]-6, IL-1β), antibodies (immunoglobulin [Ig]G, IgE), cyclooxygenase-2 (COX-2) enzyme activity, paw edema, and arthritis indices were measured using enzyme-linked immunosorbent assay and standard methods." (PMID 40342737, 2025). "Management of arthritis often necessitates the long-term use of disease-modifying agents such as methotrexate and tumor necrosis factor (TNF) inhibitors, which require careful monitoring of infection risks, drug resistance, and systemic side effects associated with immunosuppressive therapies." (PMID 41011143, 2025). "Compared with the WT-CIA group, the CD47-KO-CIA group exhibited significant decreases in the swelling of the left and right hind paws, arthritis and clinical scores, as well as levels of rheumatoid factor (RF), TNF-α, total leukocytes, neutrophils, and platelets in the blood." (PMID 40308591, 2025).
Arthritis (continued). "Notably, the TNF-α blockade using agents like infliximab has become a recommended strategy for managing severe or refractory immune-related colitis and arthritis in patients receiving ICIs." (PMID 40722787, 2025). "These experiments confirmed that SB alone mimicked key therapeutic effects of EMS, including the amelioration of arthritis, inhibition of pro-inflammatory cytokines (IL-6, TNF-α, and IL-17A), and crucially, the restoration of intestinal barrier integrity (ZO-1 and occludin)." (PMID 41309372, 2025). "Second, in some cases, TNF-α inhibitors may trigger or worsen other immune-mediated inflammatory conditions, such as new or aggravated psoriasiform skin lesions or arthritis." (PMID 41235248, 2025). "In 72/93 (77.4%) patients with arthritis flare, the joint involvement pattern was similar to that observed prior to TNFα inhibitor discontinuation, affecting joints previously involved; in 21/93 (22.6%) patients, at least one newly affected joint was observed at flare." (PMID 41153616, 2025). "It has been reported that TQ reduces TNF-α and NFκB expressions in a rat arthritis model." (PMID 38658488, 2024). "Also, using a new IL-23-driven arthritis model, we present data for a dependence on TNF, GM-CSF and CCL17 for pain and disease reinforcing their links with IL-23 in inflammation-associated pain and disease, as exemplified here in joints." (PMID 39107827, 2024). "Notably, the presence of APS autoantibodies correlated with concurrent arthritis and higher disease severity at treatment initiation in patients treated with TNF inhibitors." (PMID 38987260, 2024). "Anti-TNF-α therapy could reverse the increase in osteoclast precursors in the circulation of mice suffering from arthritis." (PMID 38362518, 2024). "The zymosan-induced arthritis model is characterized by the release of pro-inflammatory cytokines, such as tumor necrosis factor (TNF), interleukin-18 (IL-18), interleukin-1β (IL-1β), and interleukin-6 (IL-6); synovial joint hypertrophy; and leukocyte recruitment." (PMID 39194751, 2024). "Furthermore, study found that complete freund adjuvant (CFA)-induced arthritis triggered TNF-α secretion, increased JAK2 levels, and decreased transforming growth factor-β (TGF-β) levels in tissue homogenates." (PMID 39484157, 2024). "Interestingly, increased production of IL1-β and TNFα has been reported in an Nfil3−/− arthritis model." (PMID 38412963, 2024). "Another study found that a 5 mg/kg dose of TQ in rats lowered TNF-α and IL-1β levels in arthritis." (PMID 39459282, 2024). "In addition, 50, 100, and 400 mg/kg mangiferin inhibits mRNA expression of cytokine genes in the thymus and spleen of mice with induced-arthritis and lead to decreased serum levels of IL-1β, IL-6, TNF-α, and RANKL by downregulating NF-κB and activating ERK1/2." (PMID 38794160, 2024). "Our previous randomized controlled trial and animal study found that MO could improve arthritis by decreasing pro-inflammatory factors (such as TNF-α and PGE2) and increasing anti-inflammatory factors (such as IL-10)." (PMID 38410635, 2024). "This cooperation between IL-17 and TNF-α creates a positive feedback loop, amplifying the pro-inflammatory signaling and contributing to the pathogenesis of chronic inflammatory conditions like arthritis." (PMID 39687160, 2024). "Consequently, certain medications targeting arthritis, such as TNFα antagonists and interleukin-1β antagonists, exhibit potential effects on glucose metabolism by modulating glycolysis and oxidation." (PMID 38481325, 2024). "GPP may be complicated by arthritis, in which case an effective approach is to treat the arthritis according to the guidelines for treating rheumatoid arthritis, in which case methotrexate or TNF‐α inhibitors are recommended." (PMID 38105636, 2024). "Furthermore, CA treatment has been shown to decrease the expression of proinflammatory cytokines such as IL-1β, IL-6, TNF-α, IL-23, and IL-17 in various arthritis models." (PMID 39684628, 2024).
Arthritis (continued). "Additionally, we measured the levels of TNF-α, IL-1β, and IL-6 in the OA joint by ELISA measurements, which are known to be elevated with the onset of arthritis and correlate with its severity." (PMID 39076894, 2024). "Conversely, the increased expression of miR-26a reduces joint swelling, arthritis score, joint damage, chondrocyte apoptosis, release of pro-inflammatory cytokines (IL-1β, TNF-α, IL-6), and CTGF protein expression in the murine model of RA and Tohoku Hospital Pediatrics-1 (THP-1) cells." (PMID 38338785, 2024). "After characterizing the natural history of erosive activity, we next assessed the differential capacity for specific bones to recover with anti-TNF therapy towards defining biomarkers to evaluate pharmaceutical treatments efficiently and accurately in the TNF-Tg preclinical model of arthritis." (PMID 38968295, 2024). "A cohort of 24 arthritis patients was consecutively recruited before starting anti-TNFα therapy." (PMID 38256582, 2024). "In addition, the serum levels of IL-1β, TNF-α, and IL-6 showed a significant decrease for rats fed dietary OTMs, which alleviated arthritis symptoms in rats." (PMID 39330501, 2024). "Thus, both cytokines, IL-17 and IL-6, which are critical than TNF-α in arthritis, are inhibited by CRP." (PMID 38650931, 2024). "This suggests that therapies targeting inflammatory cytokines such as IL-6 and TNF may be fruitful areas of CHIKV arthritis research." (PMID 38507338, 2024). "Previous studies have reported that rheumatoid cachexia can persist in RA patients receiving biotherapy, even after arthritis symptoms improve, and treatment with anti-TNF preparations and other biologic therapies may result in elevated lipid subcomponents." (PMID 39139563, 2024). "Administration of DFHE and indomethacin reduced TNF‐α levels in CFA‐induced arthritis rats." (PMID 39479654, 2024). "The interplay between arthritis and inflammatory atherosclerosis, as well as the effects of anti-TNF biologics on these pathologies, might independently involve nAAbs." (PMID 38542402, 2024). "On the other hand, in a collagen-induced arthritis rat model, 50 mg/kg/day epigallocatechin gallate also showed the capacity to diminish TNF-α, IL-17, Nrf-2, and malondialdehyde levels and improve heme oxygenase-1, superoxide dismutase, catalase, and glutathione peroxidase levels." (PMID 38794160, 2024). "In most studies of arthritis, the TNF-α gene is overexpressed under inflammatory conditions." (PMID 38978120, 2024). "Prior work implicated TNF, GM-CSF and CCL17 in the progression of ZIA pain and disease, while Il23p19−/− mice were protected from acute T- and B-lymphocyte independent arthritis induced by recombinant TNF, GM-CSF or CCL17." (PMID 39107827, 2024). "Furthermore, this was accompanied by a parallel reduction in IgG-Fc sialylation, a phenomenon previously observed in arthritis patients treated with anti-TNF." (PMID 38793730, 2024). "The cytokine/chemokine milieu suggests that disease severity in post-CHIKV arthritis is driven by processes such as IL-6-mediated inflammation and TNF-mediated T-cell chemotaxis, in addition to an immunomodulatory response from IL-10 in an attempt to regulate immune-related damage." (PMID 38507338, 2024). "Even though JNK/MAPK pathway is also deregulated in Cyld-deficient SFs, our results and previous studies argue against a dominant pathogenic role of either JNK2 or JNK1 in TNF-mediated arthritis, without excluding, however, their synergistic role in disease." (PMID 39122678, 2024). "As expected, the positive controls, treated either with prednisolone or indomethacin, showed significantly reduced TNF-α levels regarding the arthritis control group, p < 0.001, evidencing drug efficacy in the repression of the inflammatory response elicited by adjuvant injection." (PMID 39687160, 2024).
Arthritis (continued). "Additionally, as an essential treatment for various types of arthritis, anti-TNF-α treatments play an important role in preventing the development of cavernous body dysfunction." (PMID 39022340, 2024). "Moreover, it has been suggested that MYC can regulate the production of pro-inflammatory cytokines, such as IL-1 and TNF, which are key drivers of inflammation in arthritis." (PMID 39028255, 2024). "Additionally, the overexpression of this miRNA reduces TNF-α expression, as well as clinical symptoms of synovitis in a pristine-induced arthritis (PIA) rat model." (PMID 38338785, 2024). "Thus, by integrating scRNAseq and spatial transcriptomics datasets, we identified the Marco+ peri-follicular medullary sinuses as those involved in PLN “Expansion” and “Collapse” during TNF-Tg arthritis progression." (PMID 37691918, 2023). "Although E2 significantly decreases only TNF-α-driven IL-8 upregulation, these results are in concordance with a previous observation about the opposing effect of E2 in inflammation found in several diseases such as multiple sclerosis or arthritis." (PMID 36674737, 2023). "Further, we identified a novel relationship between Ighg3 expression and severity of erosive arthritis independent of disease stage, which may relate to the variation of arthritis progression within TNF-Tg cohorts at the same age." (PMID 37691918, 2023). "Similarly, IL-18R alpha-deficient mice exhibited an attenuated form of arthritis with reduced synovial CD4 T cell and macrophage infiltration as well as lower serum levels of IL-6, IL-18, TNF-α and IFN-γ as compared to WT mice." (PMID 37415987, 2023). "NF-κB is regulated by a variety of cytokines, such as RANKL, IL-1, and TNF- α, and occupies a central position in osteolytic diseases such as periprosthetic osteolysis and arthritis, and the use of NF-κB modulators provides new ideas for the treatment of related diseases." (PMID 36644540, 2023). "The inhibition rates of IL-6 and tumor necrosis factor-α (TNF-α) were slightly higher for the SC administration; however, the loaded MNs were superior in relieving arthritis symptoms, including synovial hyperplasia, inflammatory cell infiltration, and joint cavity roughness." (PMID 37888379, 2023). "Conventional synthetic DMARDs, such as methotrexate, hydroxychloroquine, and sulfasalazine, and bDMARDs, such as TNF-α and IL-6 inhibitors, may be necessary in patients with moderate to severe arthritis that is refractory to glucocorticoid therapy." (PMID 36982715, 2023). "Reduction of arthritis scores and spleen and thymus indexes was also observed, as well as the suppression of serum levels of TNF-α, IL-1β, IL-6 and interferon gamma (IFN-γ), which could be attributed to the downregulation of inflammatory mediators." (PMID 37511889, 2023). "Patients with arthritis were more likely to choose TNF-α inhibitors." (PMID 36902720, 2023). "Given that elevated levels of IL‐6, IL‐8, and TNF‐α were previously found in CNO cohorts with higher prevalence of arthritis and skin conditions as compared to the present cohort, stratified analysis was performed for these cytokines according to the presence of these additional features." (PMID 38130757, 2023). "Active caspase 3 expression was increased in monocytes and synovial macrophages from RA patients compared with cells from healthy controls, and the use of caspase 3 inhibitors significantly blocked TNF-induced pyroptosis, which effectively alleviated arthritis in the CIA mouse model." (PMID 38106514, 2023). "The signaling downstream of the TNF, NF-κB, is one of the important signaling pathways that stimulates FLS transformation and enhances the subsequent synovial hyperplasia, degeneration of cartilage, and loss of bone during arthritis." (PMID 36835620, 2023).